PHF8 (PHD finger protein 8)
Description:
Histone lysine demethylase with selectivity for mono- and dimethylated residues. It plays an essential role in cell cycle progression and rDNA transcription. Demethylates mono- and dimethylated histone H3 'Lys-9' residue (H3K9Me1 and H3K9Me2) and monomethylated histone H4 'Lys-20' residue (H4K20Me1). Acts as a transcription activator as H3K9Me1, H3K9Me2, H3K27Me2 and H4K20Me1 are epigenetic repressive marks. Displays a very low intrinsic activity toward dimethylated H3 'Lys-27' (H3K27Me2). May also have weak activity toward dimethylated H3 'Lys-36' (H3K36Me2), however, the relevance of this result remains unsure in vivo. Involved in cell cycle progression by being required to control G1-S transition. Acts as a coactivator of rDNA transcription, by activating polymerase I (pol I) mediated transcription of rRNA genes. Specifically binds trimethylated 'Lys-4' of histone H3 (H3K4me3), affecting histone demethylase specificity: has weak activity toward H3K9Me2 in absence of H3K4me3, while it has high activity toward H3K9me2 when binding H3K4me3. Positively modulates transcription of histone demethylase KDM5C, acting synergistically with transcription factor ARX; synergy may be related to enrichment of histone H3K4me3 in regulatory elements. Required for brain development, probably by regulating expression of neuron-specific genes (By similarity).
Synonyms: KDM7B; KIAA1111; ZNF422; JHDM1F; MRXSSD
Tractability: Small molecule: a structure with a bound ligand is known; a high-quality ligand is known; it belongs to a druggable protein family. PROTAC: ubiquitination databases record sites on it; its protein half-life has been measured; a small molecule that binds it is known.
Target class: Epigenetic regulator; Jumonji domain-containing; Eraser; Lysine demethylase
Gene: Protein-coding gene on chromosome X (53,936,676 to 54,048,958, reverse strand). Ensembl gene ENSG00000172943.
Subcellular location: Nucleus; Nucleus, nucleolus
Subcellular location (Human Protein Atlas): Nucleoplasm
Pathways (Reactome):
Cell Cycle: Condensation of Prophase Chromosomes
Chromatin organization: HDMs demethylate histones
Gene Ontology:
Molecular function: chromatin binding; histone demethylase activity; histone H3K27me2/H3K27me3 demethylase activity; histone H3K36 demethylase activity; histone H3K4me3 reader activity; histone H3K9 demethylase activity; histone H3K9me/H3K9me2 demethylase activity; histone H4K20 demethylase activity; iron ion binding; protein binding; zinc ion binding; transcription coregulator activity
Biological process: G1/S transition of mitotic cell cycle; negative regulation of rDNA heterochromatin formation; positive regulation of DNA-templated transcription; positive regulation of transcription by RNA polymerase I; positive regulation of transcription by RNA polymerase II; brain development; chromatin remodeling; regulation of transcription by RNA polymerase II
Cellular component: nucleolus; nucleoplasm; nucleus
Gene-disease validity (ClinGen):
ClinGen rates the evidence that PHF8 causes each of these diseases.
syndromic X-linked intellectual disability Siderius type (X-linked): Definitive.
Homologues: Orthologues: chimpanzee PHF8 (99% identical), macaque PHF8 (99% identical), pig PHF8 (97% identical), dog PHF8 (97% identical), rabbit PHF8 (96% identical), guinea pig PHF8 (96% identical), rat Phf8 (95% identical), mouse Phf8 (95% identical), tropical clawed frog phf8 (68% identical), zebrafish phf8 (63% identical), rat Phf8l (62% identical), Caenorhabditis elegans jmjd-1.2 (19% identical), and 1 more. Paralogues in human: PHF2 (49% identical), KDM7A (37% identical), KDM2B (23% identical), KDM2A (22% identical).
Diseases named in the same sentence as PHF8 in open-access papers:
PHF8 is named in the same sentence as 77 diseases in open-access papers, as found by Europe PMC text mining. Sharing a sentence is not in itself a finding about the gene and the disease. The quoted sentences say what the papers report.
breast carcinoma (21 papers, 2018 to 2025). "To confirm these observations, we additionally set up xenograft mouse models of breast and pancreatic cancers using Phf8-deficient murine breast cancer cells (4T1) and pancreatic cancer cells (KPC)." (PMID 37454216, 2023). "At the same time, PHF8 contributes to the abundance of USP7 in breast cancer by transcriptionally facilitating its encoding genes." (PMID 34575114, 2021). "Additionally, Kaplan-Meier survival analysis of TCGA datasets indicated that elevated mRNA expression of both HER3 and PHF8 was significantly associated with poor overall survival in breast cancer patients." (PMID 41198671, 2025). "PHF8 has been reported to be overexpressed in different types of human cancers, including breast cancer, CRC, gastric cancer, prostate cancer and hepatocellular carcinoma." (PMID 40001243, 2025). "The reductions in rRNA transcription and cell numbers were suppressed by either KDM2A or PHF8 knockdown (KD) in the breast cancer cell line MCF-7." (PMID 40427554, 2025). "The c-Myc/miR-22-3p/PHF8 regulatory axis acts as a biological mechanism for the dysregulation of PHF8 expression in breast cancer and gastric cancer and plays an essential role in tumor progression." (PMID 40001243, 2025). "Our data strongly supports that the HER3/miR-34b-5p/PHF8 axis potentially serves as relevant biomarkers predictive for the survival outcomes of breast cancer patients." (PMID 41198671, 2025). "PHF8 enhances HER2-positive breast cancer progression through a synergistic interaction with HER2 signaling, regulating key oncogenic pathways." (PMID 38813086, 2024). "In HER2-positive breast cancer, PHF8 influences the tumor microenvironment by regulating cytokine IL-6 production and promoting T cell migration into the tumor." (PMID 39311138, 2024). "PHF8 acted as coactivator to induce HER2 expression in breast cancer cells and contributed in resistance to trastuzumab." (PMID 36980457, 2023). "Further research should be conducted to fully understand the role of PHF8 and other related mechanisms in breast cancer." (PMID 37174034, 2023). "PHF8 overexpression in malignant cells has been reported in several cancers, including acute lymphoblastic leukemia, breast cancer, colorectal cancer, gastric cancer, prostate cancer, and hepatocellular carcinoma." (PMID 35179962, 2022). "A significant body of evidence has highlighted a potential role for PHF8 in advanced stages of breast cancer." (PMID 31137748, 2019). "Data from the TCGA (The cancer genomic atlas) analysis revealed that PHF8 is upregulated in breast cancer malignancies, more specifically in invasive ductal and lobular breast carcinoma, invasive stroma and other rare types of breast carcinoma." (PMID 31137748, 2019). "Given the well-established role of HER3 in HER2-positive breast cancer progression and therapeutic resistance, it is conceivable to hypothesize that PHF8 potentially acts as a key downstream mediator of HER3 signaling as well." (PMID 41198671, 2025). "Moreover, our study reveals a significantly positive correlation between HER3 and PHF8 in TNBC specimens and clinic relevance of the HER3/miR-34b-5p/PHF8 axis in association with the survival outcomes of breast cancer patients." (PMID 41198671, 2025). "Clinically, HER3 and PHF8 expression levels were positively correlated in TNBC tissue specimens, and TCGA dataset analyses indicated that the HER3/miR-34b-5p/PHF8 axis is significantly associated with poor survival outcomes in breast cancer patients." (PMID 41198671, 2025). "Here, we showed that KDM2A together with PHF8 controlled rRNA transcription in breast cancer cells." (PMID 40427554, 2025). "Interestingly, recent studies have revealed that PHF8 is aberrant in several human malignancies, including breast cancer." (PMID 40427554, 2025). "Certain scholars have discovered that PHF8 inhibitors may be used as synergistic reagents for HER2-positive breast cancer patients to overcome resistance to anti-HER2 therapies." (PMID 39311138, 2024).
breast carcinoma (continued). "Additionally, blocking the PHF8-TOPBP1 (DNA topoisomerase II binding protein 1) connection would trigger the vulnerability to chemotherapeutics in breast cancer." (PMID 37174034, 2023). "Increased sensitivity to cisplatin treatment was also observed in MDA-MB-231 breast cancer cells by knocking out the PHD finger protein 8 (PHF8) gene, suggesting that cisplatin resistance has multigenic character, with new genes been validated as potential targets for treatment-refractory cancers." (PMID 36139356, 2022). "PHF8, one of the histone demethylases, is upregulated in some types of tumors, such as neuroendocrine prostate cancer, non-small-cancer lung carcinoma, hepatocellular carcinoma, gastric cancer, and breast cancer." (PMID 36518887, 2022). "Moreover, upregulation of USP7, PHF8, and cyclin A2 has also been found in breast cancers, colon and rectum cancers." (PMID 34869041, 2021). "Indeed, USP7, PHF8 and cyclin A2 were all found to be upregulated in several breast cancers, as well as in colon and rectum cancers, compared to adjacent tissues." (PMID 32850836, 2020). "Thus, exploring the potential of the selective inhibition of USP7 and/or PHF8 enzyme activity, particularly in combination with chemotherapy or radiation therapy, may be worthwhile for treatment refinement of breast cancer." (PMID 39311138, 2024). "Here, we found that PHD finger protein 8 (PHF8) interacted with KDM2A and contributed to the reduction in rRNA transcription and cell proliferation by 2-deoxy-D-glucose in a breast cancer cell line, MCF-7." (PMID 40427554, 2025). "For instance, both USP7 and PHF8 exhibit high expression in breast cancer and DSB repair relies on PHF8 stabilization, which is enforced by USP7." (PMID 39311138, 2024). "Previous evidence demonstrated that PHF8 contributes to EMT and promotes malignant progression and metastasis in breast cancer, prostate cancer and liver cancer." (PMID 39048555, 2024). "Consistently, PHF8 was found to be a direct target of miR-22 and is thus mediated by MYC to promote the epithelial–mesenchymal transition (EMT) and tumorigenesis in breast cancer." (PMID 39311138, 2024). "PHF8 is involved in HER2 transcriptional regulation via the maintenance of H3K4me3 levels, which is required for HER2 transcriptional regulation in breast cancer cells." (PMID 39311138, 2024). "In breast cancer, a functional link between USP7 and PHF8 was seen through their interaction and a positive feedback mechanism." (PMID 34577547, 2021). "In summary, the ATM/ZEB1/USP7/CHK1, miR-200c/LINC02582/USP7/CHK1, USP7/PHF8, UCHL3/RAD51, USP52/ASF1A, and UCHL1/HIF-1 signaling axis are potential targets to improve the radiosensitivity of breast cancer." (PMID 34575114, 2021). "PHF8 is stabilized by USP7 through deubiquitination, resulting in increased expression of cyclin A2, which promotes the proliferation of breast cancer cells and accelerates tumor growth." (PMID 34575114, 2021). "In MCF7 breast cancer cells it was observed that USP7 deubiquitinates and stabilizes PHF8 during DNA damage response, contributing to the activation of DNA repair mechanisms." (PMID 34577547, 2021). "USP7 has also been suggested as a potential target for sensitization in breast cancer treatment, where USP7 is frequently upregulated and confers resistance to genotoxic insult, by stabilizing PHF8." (PMID 32850836, 2020). "Similarly, PHF8’s involvement in castration-resistant prostate cancer via the AR signaling axis and its role in promoting HER2-positive breast cancer and melanoma metastasis highlight its significance in tumor progression and therapy resistance." (PMID 38813086, 2024). "In addition, given the essential roles of PHF8 and CHK1 that act as USP7 substrates in DNA damage response, combination of USP7 inhibitors and chemotherapy/radiotherapy may reduce breast cancer cell resistance, which is expected to accelerate the development of breast cancer therapy." (PMID 34869041, 2021).
hepatocellular carcinoma (15 papers, 2018 to 2026). A malignant tumor that arises from hepatocytes. "PHF8 (KDM7B), as a histone demethylase, is responsible for demethylation of H3K9me1/2, H3K27me2 and H4K20me1, allowing transcription of downstream genes, and is involved in hepatocellular carcinoma, X-chromosome-linked intellectual disability (XLID), melanoma, esophageal cancer and so on." (PMID 35633416, 2022). "PHF8/KDM7B overexpression has been shown to act as an oncoprotein in a variety of cancers, including, hepatocellular carcinoma, laryngeal and hypopharyngeal squamous cell carcinoma, and non-small cell lung cancer." (PMID 37218871, 2023). "In hepatocellular carcinomas, PHF8 expression was observed in nuclei, and a higher expression of n-PHF8 predicted the shorter survival of patients." (PMID 36980457, 2023). "MTF2 (metal regulatory transcription factor 2), for example, was shown to induce EMT by transcriptionally activating Snail in hepatocellular carcinoma, whereas PHF8 (PHD finger protein 8) is an enzyme that demethylates the H3K9, H3K27, and H4K20 lysine residues." (PMID 32831131, 2020). "However, little is known about PHF8 roles in hepatocellular carcinoma (HCC) and regulating E-cadherin expression." (PMID 30180906, 2018). "The expression of PHF8 in HCC tissues was significantly higher than that in adjacent normal tissues, and was significantly related to the malignant degree and overall survival rate of HCC, suggesting that PHF8 plays an important role in the occurrence and development of hepatocellular carcinoma." (PMID 32441881, 2020).
prostate carcinoma (13 papers, 2013 to 2025). A carcinoma that arises from epithelial cells of the prostate gland. "PHF8 has been implicated in promoting different malignancies including prostate cancer, esophagus cancer, and lung cancer." (PMID 33009820, 2021). "Overexpression or mutation of JmjC domain-containing KDMs has also been linked to many types of cancer, including PHF8 in prostate cancer." (PMID 24146981, 2013). "Recently, PHF8 was found to have an effect on prostate cancer cell proliferation, migration, and invasion, in which the integrin pathway is linked to its oncogene function in human prostate cancer." (PMID 24146981, 2013). "Moreover, elevated PHF8 is associated with higher grade prostate cancers and unfavorable outcomes." (PMID 27991916, 2016). "This HIFs/AR/PHF8 axis accelerates prostate cancer progression and is a potential therapeutic target for CRPC treatment." (PMID 39311138, 2024). "PHF8 influences prostate cancer progression and resistance mechanisms by integrating into the androgen receptor signaling axis, a key pathway in castration-resistant prostate cancer (CRPC)." (PMID 38813086, 2024). "For example, PHF8 upregulates miR-125b expression to participate in the regulation of the proliferation and apoptosis of prostate cancer cells." (PMID 39311138, 2024). "In prostate cancer, miR-22 can cause partial NED and directly inhibit PHF8 translation by targeting the 3′-untranslated region (3′-UTR)." (PMID 39311138, 2024). "PHF8 overexpression is reported in several kinds of solid and hematologic malignancies, including cancer of the prostate, breast, gastric, liver, lung, and colon, together with acute promyelocytic leukemia (APL) and acute myeloid leukemia (AML)." (PMID 39311138, 2024). "NEDD4L inhibits the proliferation of prostate cancer cells by degrading plant homeodomain finger protein 8 (PHF8/KDM7B) through the ubiquitin–proteasome system." (PMID 38027016, 2023). "To investigate the potential role of PHF8 in prostate cancer initiation and progression, we crossed female Phf8 knockout mice (Phf8X−/−) with male TRAMP mice to obtain male Phf8 knockout TRAMP mice (TRAMP/Phf8‐KO)." (PMID 33009820, 2021). "We previously used a prostate cancer cell line‐based model to demonstrate that PHF8, by serving as an AR coactivator, can enhance CRPC progression." (PMID 33009820, 2021). "Together, these results suggest that castration treatment can lead to local ischemia/hypoxia in prostate cancer tissues and a concurrent up-regulation of HIF1α and HIF2α as well as PHF8." (PMID 27991916, 2016). "Having established that hypoxia induced PHF8 expression in prostate cancer cells, we next determined if PHF8 regulates histone methylation in prostate cancer cells." (PMID 27991916, 2016). "Our study thus provides a molecular explanation for the correlation between elevated PHF8 expression and prostate cancer progression." (PMID 27991916, 2016). "Altogether, our data suggest the existence of a HIF/PHF8/AR axis that promotes prostate cancer progression and allows us to propose a working model." (PMID 27991916, 2016). "The elevated levels of PHF8 augment AR transcriptional activity and are likely to promote prostate cancer progression at least in part through its ability to promote the AR signaling pathway." (PMID 27991916, 2016). "To test if endogenous PHF8 and AR interact with each other, we prepared whole-cell extracts from the AR positive prostate cancer cell line, LNCaP." (PMID 27991916, 2016). "Our findings support a working model in which hypoxia in castrated prostate cancer activates HIF transcription factors which then induces PHF8 expression." (PMID 27991916, 2016). "To substantiate this observation, we compared the levels of PHF8, HIF1α and HIF2α in pre- and post-castration prostate cancer tissues from 14 patients with advanced prostate cancer by western blot analysis." (PMID 27991916, 2016). "PHF8 elevation was abolished in HIF1α and HIF2α knockdown prostate cancer cells." (PMID 39311138, 2024).